SMIM20 (small integral membrane protein 20)
Description:
[Small integral membrane protein 20]: Component of the MITRAC (mitochondrial translation regulation assembly intermediate of cytochrome c oxidase complex) complex, that regulates cytochrome c oxidase assembly. Promotes the progression of complex assembly after the association of MT-CO1/COX1 with COX4I1 and COX6C. Chaperone-like assembly factor required to stabilize newly synthesized MT-CO1/COX1 and to prevent its premature turnover. [Phoenixin-14]: Peptide involved in a broad spectrum of regulatory functions (By similarity). Is a ligand for GPR173 (By similarity). As part of the reproductive cycle, it regulates gonadotropin-releasing hormone (GnRH) signaling in the hypothalamus and pituitary gland which augments the release of luteinizing hormone (By similarity). Plays a protective role in memory retention through activation of GNRHR (By similarity). Regulates the secretion of AVP by hypothalamic neurons (By similarity). Plays a role in the transduction of the itch sensation (By similarity). Induces anxiolytic effects, reducing behavior associated with anxiety (By similarity). Regulates food intake as well as satiation and satiety (By similarity). In the ovary, it regulates follicular growth by stimulating granulosa cell proliferation by increasing the expression of GPR173, CREB1, CYP19A1, KITLG, FSHR, and LHCGR. It also increases the production of estradiol (E2). In the heart, it regulates contractility and relaxation (By similarity). It also plays a cardioprotective role during ischemia, where it activates the SAFE and RISK pathways (By similarity). Stimulates the proliferation and differentiation of preadipocytes (By similarity). In pancreatic islet cells, it induces proliferation of islet cells as well as the production of INS (By similarity). [Phoenixin-20]: Peptide involved in a broad spectrum of regulatory functions (By similarity). Is a ligand for GPR173 (By similarity). As part of the reproductive cycle, it regulates gonadotropin-releasing hormone (GnRH) signaling in the hypothalamus and pituitary gland which augments the release of luteinizing hormone (By similarity). Plays a protective role in memory retention through activation of GNRHR (By similarity). Regulates the secretion of AVP by hypothalamic neurons (By similarity). Plays a role in the transduction of the itch sensation (By similarity). Induces anxiolytic effects, reducing behavior associated with anxiety (By similarity). Regulates food intake as well as satiation and satiety (By similarity). In the ovary, it regulates follicular growth by stimulating granulosa cell proliferation by increasing the expression of GPR173, CREB1, CYP19A1, KITLG, FSHR, and LHCGR. It also increases the production of estradiol (E2). In the heart, it regulates contractility and relaxation (By similarity). It also plays a cardioprotective role during ischemia, where it activates the SAFE and RISK pathways (By similarity). Stimulates the proliferation and differentiation of preadipocytes (By similarity). In pancreatic islet cells, it induces proliferation of islet cells as well as the production of INS (By similarity).
Synonyms: MITRAC7; C4orf52; PNX
Tractability: Antibody: UniProt places it where antibodies can reach, with medium confidence; UniProt predicts a signal peptide or a membrane-spanning region; its Gene Ontology location is reachable by antibodies, with medium confidence. PROTAC: its protein half-life has been measured.
Gene: Protein-coding gene on chromosome 4 (25,861,830 to 25,929,813, forward strand). Ensembl gene ENSG00000250317.
Subcellular location: Mitochondrion inner membrane (Small integral membrane protein 20); Secreted (Phoenixin-14); Secreted (Phoenixin-20)
Subcellular location (Human Protein Atlas): Cytosol; Nucleoplasm; Nucleoli; Predicted to be secreted
Pathways (Reactome):
Metabolism: Complex IV assembly
Gene Ontology:
Molecular function: protein binding
Biological process: mitochondrial respiratory chain complex IV assembly
Cellular component: mitochondrial inner membrane; mitochondrion; extracellular region; membrane
Genetic constraint (gnomAD): Loss-of-function variants: 3 observed, 8.54 expected, observed/expected ratio (o/e) 0.35, 90% interval 0.16 to 0.91. That is too few expected variants to judge how well the gene tolerates losing a copy. Missense variants: 85 observed, 87.43 expected, observed/expected ratio (o/e) 0.97, 90% interval 0.81 to 1.16. Synonymous variants: 44 observed, 35.05 expected, observed/expected ratio (o/e) 1.26, 90% interval 0.99 to 1.61.
Homologues: Orthologues: guinea pig SMIM20 (97% identical), macaque C4orf52 (96% identical), mouse Smim20 (91% identical), dog SMIM20 (88% identical), rat Smim20 (75% identical), tropical clawed frog smim20 (67% identical), zebrafish smim20 (57% identical).
Diseases named in the same sentence as SMIM20 in open-access papers:
SMIM20 is named in the same sentence as 20 diseases in open-access papers, as found by Europe PMC text mining. Sharing a sentence is not in itself a finding about the gene and the disease. The quoted sentences say what the papers report.
endometriosis (5 papers, 2021 to 2025). The growth of functional endometrial tissue in anatomic sites outside the uterine body. "The aim of the study was to determine PNX, FSH, LH, and 17β-estradiol association in women with endometriosis, and the expression of SMIM20/PNX signaling via GPR173." (PMID 34680544, 2021). "In view of the reduced expression of the GnRH receptor, and GnRH itself, in the eutopic endometrium of women with endometriosis, altered expression of SMIM20 and the GPR173 receptor in the eutopic and ectopic endometrium of these women is expected." (PMID 34680544, 2021). "Interestingly, gonadotropin-releasing hormone analogs, used among others in the treatment of endometriosis, increase small integral membrane protein 20 gene expression and decrease GPR173 in the rats’ hypothalamus, pituitary, and ovaries." (PMID 39857742, 2025). "Moreover, GnRH analogs are often used to treat endometriosis and have been found to increase SMIM20 expression and decrease GPR173 receptor expression in the rat hypothalamus, pituitary, and ovaries." (PMID 34680544, 2021). "These new insights may provide not only a better understanding of endometriosis pathophysiology but also lay the potential groundwork for the diagnosis and treatment of endometriosis by targeting SMIM20/PNX." (PMID 34680544, 2021). "Further studies have shown that endometrial cells increase the synthesis of the SMIM20 precursor in response to low PNX levels, which may suggest a potential role of PNX in improving epithelial dysfunction and may be an effective strategy for using PNX in the treatment of endometriosis." (PMID 41369336, 2025).
Obesity (5 papers, 2022 to 2025). Accumulation of substantial excess body fat. "We propose that obesity-related expansion of adipose tissue enhances Smim20/PNX expression, thereby accelerating HPGA activation and pubertal onset." (PMID 41356008, 2025). "The aim was to determine the link between HFD-induced prepubertal obesity and accelerated puberty in male rats and to explore the role of Smim20/PNX in this process." (PMID 41356008, 2025). "The findings suggest that obesity may accelerate pubertal onset, and that Smim20/PNX may participate in regulating pubertal development in males." (PMID 41356008, 2025).
SMIM20 also shares sentences with these, for which no sentence is quoted: polycystic ovary syndrome (7 papers); Anxiety (3); pyometra (2); cataract (1); depression (1); diabetes (1); diabetic retinopathy (1); heart failure (1); infertile (1); ischemia (1); metabolic disorders (1); mood disorder (1); non-alcoholic fatty liver disease (1); partial epilepsy (1); psychiatric disorder (1); pulmonary arterial hypertension (1); type 2 diabetes (1); uterus disorders (1).